IL6 (interleukin 6)
Diseases named in the same sentence as IL6 in open-access papers (continued):
Sharing a sentence is not in itself a finding about the gene and the disease.
depression (continued). "Clinical studies have revealed that circulating markers of immune activation, such as increased numbers of granulocytes and monocytes and elevated levels of TNF-α and IL-6, are observed in the blood of individuals with depression." (PMID 31540304, 2019). "Some other studies also found a positive correlation between the severity of depression and the serum concentrations of IL-6." (PMID 30899619, 2019). "Other recent meta-analyses revealed evidence of increased CSF levels of IL-1β in schizophrenia and bipolar disorders and increased levels of IL-6 and IL-8 in schizophrenia and depression." (PMID 30116031, 2019). "An interesting study demonstrated positive correlations between Th1 (IL-6) and Th2 (IL-10) cytokines with depression, anxiety, and perceived stress in women during mid-pregnancy [14–28 gestation weeks (gwks)]." (PMID 30943938, 2019). "In the present study, the LPS-induced depression model produced the proinflammatory cytokines (IL-6 and TNF-α), and IL-6 positive cells were identified primarily in the dentate gyrus (DG) of rats." (PMID 31798446, 2019). "Blood IL-6 levels are significantly higher in patients with depression; at the same time, CKD is frequently accompanied by depressed mood." (PMID 31847451, 2019). "The reserpine-induced rat depression model significantly elevated the expression levels of IL-1β, IL-6, and TNF-α in the serum, liver and hippocampus of rats compared with the control group (P < 0.01 or P < 0.05)." (PMID 32009949, 2019). "Clinical studies measuring sIL6R in unipolar depression are still sparse, but two meta-analyses in bipolar depression have reported that circulating levels of IL-6 and sIL6R were higher in patients than in healthy controls." (PMID 31362361, 2019). "It indicated that serum levels of IL-1β and IL-6 significantly increased in GC patients with depression." (PMID 31396300, 2019). "Patients with depressive disorders were reported to have a higher serum concentration of inflammatory markers, including interleukin (IL)-6, tumor necrosis factor (TNF)-α and IL-1β, compared with those without depressive disorders." (PMID 31765424, 2019). "Animal models of depressive disorders have shown an increase in pro-inflammatory markers, such as interleukin-6 (IL-6), interleukin-1β (IL-1β) and tumor necrosis factor alpha (TNF-α)." (PMID 30678337, 2019). "Elevated IL-6 and/or CRP has been associated with depression, autism, schizophrenia and related psychoses." (PMID 29198208, 2018). "The involvement of peripheral IL-6 in elderly with depression reflects a high proportion of metabolic comorbidities which are modifiable." (PMID 30104698, 2018). "Other studies have not found any correlations between L-6, IL-8, IL-10, TNF-α, FIQ and depression, IL-6 and depression or anxiety, IL-6 and pain score, FIQ, or TNF-α." (PMID 29849487, 2018). "Meta-analyses have indicated that C-reactive protein (CRP), interleukin-6 (IL-6), and TNF-α are the most robust evidence-based inflammatory markers associated with depression." (PMID 30429764, 2018). "As IL-1β, IFN-α/γ, TNF-α, and IL-6 have also been related to the onset and development of depression." (PMID 30662368, 2018). "Well-known inflammatory cytokines characteristic of AR or RS, such as IL-6 and IFN-γ, have been shown to be linked to depression via modulation of central nervous system (CNS) processes." (PMID 29324857, 2018). "A meta-analysis indicated that the inflammatory markers associated with depression are TNFα, IL-1, IL-6 and CRP and there are many reports showing the association between serum IL-6 increase and depression." (PMID 30423923, 2018). "The acute-phase protein CRP and the proinflammatory cytokine IL-6 are the most frequently investigated biomarkers of inflammation in cross-sectional and prospective studies on depression." (PMID 29520075, 2018).
depression (continued). "A great deal of research has shown that proinflammatory cytokines, such as IL-6, are possibly contributed to the emergence of depression-like symptoms and sleep perturbations." (PMID 29607310, 2018). "Based on a small number of cases the findings need replication in other samples, but provide further evidence that the IL-6/IL6R pathways are involved in pathogenesis of severe depression and psychosis." (PMID 29197507, 2018). "Collectively, these data demonstrate that IL-6 and Rac1 can each modulate synaptic plasticity in neurons from NAc, supporting these mechanisms as targets for stress-induced depression." (PMID 29396460, 2018). "LPS transiently increased interleukin-6 and tumor necrosis factor-α, sickness symptoms, body temperature and self-reported fatigue, and depression post injection relative to baseline and placebo." (PMID 28948979, 2018). "Peripheral inflammatory response can lead to depression, the inflammatory factors (IL-6, TNF-α and CRP) are mainly synthesized by monocytes and produce inflammatory response and promote immune response." (PMID 30181997, 2018). "Given that an acute episode of depression is also accompanied by increased serum IL-6 levels, the results suggest increased IL-6 trans-signaling occurs in acute depression." (PMID 29103192, 2018). "In contrast, other studies observed a positive correlation between hostility and IL-6 or TNF-α only in individuals with low levels of depression." (PMID 29623033, 2018). "Similar to the findings from aggression studies, increased circulating IL-6 has been observed in humans suffering from major depression." (PMID 29623033, 2018). "TNF-α is known to be increased in anxiety disorder, posttraumatic stress disorder and major depression, where TNF-α and IL-6 are also associated with a smaller chance to respond to treatment with SSRIs." (PMID 30241502, 2018). "After correction for multiple testing, only peripheral levels of IL-6 remained significantly higher in elderly with depression." (PMID 30104698, 2018). "Longitudinal studies have shown that higher serum concentrations of IL-6 increase future risks of heart disease, diabetes mellitus, depression and psychosis." (PMID 29197507, 2018). "Previously, some other studies have reported correlations between IL-6 and IL-17A and pain and depression, but few of these have used multivariate analyses." (PMID 29849487, 2018). "Our evidence suggests that both DHCA and Mal-gluc contribute to resilience against the development of depression-like phenotypes by modulating, respectively, pathological mechanisms relating to IL-6 and Rac1." (PMID 29396460, 2018). "Median values for another pro-inflammatory cytokine, IL-6, were also highest in the Abuse group and lowest in the Depression group (p = 0.04)." (PMID 29894487, 2018). "Increased levels of hippocampal IL-6 were observed in murine models of depression following induction of seasonal affective disorder, whereas deletion of IL-6 resulted in a reduction of depression symptomology." (PMID 29941796, 2018). "Injecting mice with IL-6, which controls serotonin transporter levels and consequently serotonin reuptake, leads to depression-like behaviour." (PMID 29197507, 2018). "Increased circulating hs-CRP and IL-6 concentrations compared with controls have been consistently reported in schizophrenia, depression, and other psychiatric disorders." (PMID 30322824, 2018). "We also observed that CRP and IL-6 correlated with lower score on HADS depression items in the control group (p = 0.009, β = −0.655 and p = 0.003, β = −0.630)." (PMID 30185816, 2018). "Adolescents with history of more severe abuse and depression had higher IL-6 levels in the second trimester compared to those with less severe abuse and milder depression." (PMID 30127754, 2018). "Other meta-analyses have suggested associations between depression and inflammatory markers, such as C-reactive protein (CRP), IL-6 and, to a lesser extent, IL-1." (PMID 30400354, 2018).
depression (continued). "Studies found that elevated levels of cytokines such as interleukin- (IL-) 1β, IL-6, and tumor necrosis factor-α (TNF-α) are closely associated with the pathogenesis of depression." (PMID 29765402, 2018). "Other studies have also found increased levels of serum IL-6 in patients with depression, which were decreased or unchanged after antidepressant treatment." (PMID 29856741, 2018). "The field now needs RCTs of cytokine modulators targeting IL-6/IL6R for patients with depression and psychosis, specifically those with evidence of inflammation, to translate these results into benefits for patients." (PMID 29197507, 2018). "The inflammatory cytokines in the central nervous system, specially IL-6, can lead to depression through neuroinflammation." (PMID 30400354, 2018). "It has been postulated that increased levels of IL-6 and IL-1β are involved in the pathogenesis of Alzheimer’s disease and major depressive disorders." (PMID 30096932, 2018). "We report that the variant is associated with increased IL-6 but decreased CRP levels assessed in childhood, and is protective for severe depression and/or psychosis assessed in early adulthood." (PMID 29197507, 2018). "A similar pattern was observed in another study, where the authors found a significant interaction between hostility and depression symptoms for serum IL-6 and CRP." (PMID 29623033, 2018). "Our results suggest that peripheral pro-inflammatory marker IL-6 is more likely to be increased in depression as compared to Alzheimer’s disease in elderly." (PMID 30104698, 2018). "This impairment in BBB permeability allows more blood IL-6 to enter the brain and promotes depression-like behaviors following social defeat." (PMID 29623033, 2018). "Based on human population-based data our findings provide further evidence that the IL-6/IL6R pathways are involved in pathogenesis of severe depression and psychosis." (PMID 29197507, 2018). "Further research is needed to examine the moderating and mediating effects of BMI on depression with additional biomarkers, e.g., malondialdehyde, F2-isoprostanes, 8-hydroxy 2′-deoxyguanosine, neuropeptide Y, adiponectin, IL-6, TNF-α, and IL-17." (PMID 30524737, 2018). "The degradation of serotonergic neurons induced by LPS in the fetus is attributed to the increased levels of interleukin (IL)-6 and tumor necrosis factor (TNFα) as well as to anxiety and depression in children." (PMID 30469423, 2018). "Another study in patients with coronary heart disease and depression was unable to find that increased serum IL-6 levels predict a poor response to treatment with antidepressants." (PMID 29103192, 2018). "CRP is an archetypal acute phase protein and IL-6 is a pleotropic proinflammatory cytokine, both of which have been studied extensively in depression and shown to be elevated in acutely unwell patients compared with controls." (PMID 29140226, 2018). "Intervention studies targeting the IL-6 system are required for a better understanding of the relationship between inflammation and depression." (PMID 30244217, 2018). "We have examined the association of Asp358Ala with diagnosis of depression and psychosis, serum IL-6, CRP levels, and a number of risk factors commonly linked with inflammation, depression or psychosis." (PMID 29197507, 2018). "Compared to IL-6, reports indicated that the relationships between depression and TNF-α, IL-12 and IL-10 are few." (PMID 30400354, 2018). "Elderly with depression were significantly higher in their peripheral IL-6 levels than control participants (pooled SMD with random-effects model: 0.377, 95% CI: 0.156–0.598, z = 3.348, p < 0.001)." (PMID 30104698, 2018). "Concentrations of the pro-inflammatory cytokine IL-6 were highest in the Abuse+Depression group (1.10 log pg/mL), followed by Abuse (1.08 log pg/mL), Depression (0.97 log pg/mL) and Control (0.58 log pg/mL) (p = 0.05)." (PMID 29894487, 2018).
depression (continued). "Prospective cohort studies indicate a correlation between elevated levels of IL-6/CRP and subsequent risk of physical and neuropsychiatric illnesses such as cancers, coronary heart disease, type 2 diabetes, Alzheimer's disease, depression and psychosis." (PMID 29198208, 2018). "A study claim that depression is related with the increase of inflammatory bio-markers such as IL-6, TNF-α and C-reactive protein." (PMID 29896129, 2018). "If combined, the treatment of DHCA and Mal-gluc reduced IL-6 level to baseline and simultaneously increased Rac1 expression, which contribute to the resilience against the development of depression-like phenotypes in mice." (PMID 30154441, 2018). "Trials of IL-6 inhibition are being conducted in patients with depressive disorder using anti-IL-6 Ab sirukumab phase II (NCT02473289) and anti-IL-6R Ab TCZ phase II (NCT02660528)." (PMID 30423923, 2018). "A limited number of studies have demonstrated increased levels of cytokines (IL-6, IL-8,TNFα) in cancer patients with depression." (PMID 30266081, 2018). "In a chronic stress-induced depression model, 10 mg/kg ketamine injection showed a rapid antidepressant effect and effectively reduced the protein expression levels of IL-6, IL-1β, and TNF-α." (PMID 28373844, 2017). "Increased mean plasma levels of pro-inflammatory cytokines such as the tumor necrosis factor alpha (TNF-α), interleukin-1 (IL-1) and interleukin-6 (IL-6) have been reported in patients with clinical depression." (PMID 28415673, 2017). "Accumulating evidence suggests that pro-inflammatory cytokines such as interleukin-6 (IL-6) have an important role in the pathogenesis of depression." (PMID 28556833, 2017). "IL1a is a potent inflammatory cytokine and a key mediator of brain inflammation whereas IL6 is a pro-inflammatory cytokine involved in depression." (PMID 28659758, 2017). "Individuals with depression (current MDD or high depressive symptoms) had lower IL6 methylation levels at one of the four sites investigated, however the effect size was small (∆ 2.4%, SE 0.009, p = 0.006)." (PMID 29070016, 2017). "As a consequence, despite of the high level of cortisol, levels of TNF-α, IL-1b and IL-6 increase what is a common characteristic of major depression." (PMID 28738849, 2017). "It is now evident that depression is the clinical expression of peripheral cell-mediated activation, inflammation (increased levels of proinflammatory cytokines, such as IL-6 and TNF-α), and induction of oxidative and nitrosative stress pathways." (PMID 28127570, 2017). "Rats with depression-like phenotype displayed increased levels of cytokines (IL-1β, IL-6, TNF-α, IL-4 and IL-10) in the PFC compared with sham-operated and rats without depression-like phenotype (P < 0.05) on day 21 after SNI surgery." (PMID 28600519, 2017). "Males with major depression and a history of early life stress display an increased IL-6 response to social stress." (PMID 28753980, 2017). "Rats with depression-like phenotype displayed higher levels of pro-inflammatory cytokines (e.g., interleukin (IL)-1β, IL-6) as well as imbalance of pro/anti-inflammatory cytokines compared with rats without depression-like phenotype and sham-operated rats." (PMID 28600519, 2017). "It is well established that there is a link between inflammation and depression, with several studies reporting increased circulating levels of the pro-inflammatory cytokine, interleukin-6 (IL6), in depressed individuals." (PMID 29070016, 2017). "Elevated CSF IL-6, IL-8, and TNF seem to have the strongest associations with depression, apathy, and disinhibition at 6–12 months." (PMID 28740480, 2017). "IL6 biosynthesis is commonly upregulated in human patients suffering from major depressive disorder, and increased circulating IL6 protein was reported in chronically distressed domestic chicks." (PMID 29211774, 2017).
depression (continued). "Increased expression of pro-inflammatory cytokines IL-1β, IL-6, TNF-α, as well as interferon gamma (IFN-γ), and C-reactive protein (CRP) is repeatedly observed in patients suffering from depression and has been associated with specific symptoms of depression." (PMID 28239408, 2017). "A connection between depression and immune parameters, such as, pro-inflammatory cytokines (e.g., interleukin (IL)-1 and IL-6) has been explored." (PMID 28253340, 2017). "A study of exercise for depression found a relationship between high baseline levels of IL-6 and greater reductions in posttreatment depression severity." (PMID 28894426, 2017). "Although 5-ASA is a known anti-inflammatory agent, neither treatment with SSZ nor 5-ASA/SP prevented tumour-induced increases in serum levels of interleukin-1β (IL-1β) and IL-6, which are indicated in depressive disorders." (PMID 28120908, 2017). "The increased level of IL-6 has been shown in patients with depressive disorder and it probably influences the metabolism of serotonin in CNS, decreasing the availability of tryptophan in the blood." (PMID 26649857, 2017). "Immunotherapy involving the administration of interferon-α for the treatment of hepatitis C or cancer has been shown to induce the production of proinflammatory cytokines such as interleukin-6 and depression among a considerable number of patients." (PMID 27129131, 2016). "Rather, significant predictors of depression chronicity were elevated: interleukin-6 (IL-6), low high-density lipoprotein (HDL)-cholesterol, hypertriglyceridemia, and hyperglycemia." (PMID 26771598, 2016). "Among 3024 subjects between 70 and 79 years of age, those who scored higher on a standardized depression scale also had significantly higher levels of IL-6, TNF, and CRP." (PMID 28030615, 2016). "Cancer patients often experience high levels of anxiety and depression, and this can affect the immune system through glucocorticoid resistance and decreased interleukin 6 level." (PMID 27780931, 2016). "Since IL-6 has a prominent role in cognitive function, and in the internalization of various stress types, it is possible that IL-6 is involved in depression-specific changes of the brain structure." (PMID 26821321, 2016). "In a 12-year prospective study of British civil servants, increased IL-6 levels at baseline predicted cognitive symptoms of depression at follow-up." (PMID 28082989, 2016). "Patients with depression show higher serum levels of pro-inflammatory cytokines than a normal group, including IL-1, IL-6, IL-8, IL-12, interferon-γ, and TNF-α." (PMID 27347982, 2016). "Interleukin-6 (IL-6) has emerged as a potent biomarker for depression as its elevated plasma levels in patients with clinical depression have been confirmed by meta-analyses." (PMID 26821321, 2016). "Finally, other proposed mechanisms by which insomnia might increase the risk of depression included increasing levels of inflammatory markers, such as C-reactive protein and interleukin-6 (IL-6), which indicated low-level systemic inflammation was a predictor of depression development." (PMID 27816065, 2016). "At baseline, elevated levels of IL-8 and IL-6 were related to higher levels of depressive symptoms, as assessed using the Geriatric Depression Scale (GDS) (odds ratio (OR) = 1.042; p = 0.025 and OR = 1.041; p = 0.035, respectively)." (PMID 27918465, 2016). "Further studies are required to assess the role of IL-6 and NF-κB in rat prefrontal cortex in chronic stress and depression." (PMID 28074100, 2016). "In the present study, we report elevation of Il6 in the prefrontal cortex (PFC) of a genetic rat model of depression, the Flinders Sensitive Line (FSL) compared to the control Flinders Resistant Line." (PMID 27529677, 2016). "Associations have been reported between IL-6 or CRP and depression, hopelessness, vital exhaustion, negative affect, and psychological distress." (PMID 26979423, 2016).